MTOR (mechanistic target of rapamycin kinase)
Diseases named in the same sentence as MTOR in open-access papers (continued):
Sharing a sentence is not in itself a finding about the gene and the disease.
breast cancer (continued). "The mTOR signaling pathway also provides a feedback mechanism to regulate OGT and O-GlcNAc levels in breast cancer cells." (PMID 37838167, 2023). "Besides, under hypoxia, Bca cells also depended on glutamine required for cell growth, and pharmacological inhibition of HIF-regulated SLC1A5 using V-9302 could block breast cancer cell growth, along with decreased mTOR signaling and increased ROS levels and autophagy." (PMID 36967443, 2023). "For example, mTOR is an important regulator of the SASP, and the mTOR inhibitor temsirolimus promotes senescent cancer cell death and suppresses prostate and breast cancer cells." (PMID 37771436, 2023). "Data from animal models have shown that PA decreases the protein expression levels of activated mTOR, AKT, and phosphorylated P70S6K (p-P70S6K)—important factors in the mTOR signaling pathway—in mammary carcinomas." (PMID 36895729, 2023). "These genes were also enriched in the PI3K/Akt, Notch1/Hes1 or Akt1/mTOR signaling pathways and were reported to be correlated with LNM in breast cancer." (PMID 36644636, 2022). "In breast cancer, BBR reversed chemoresistance through inhibition of the efflux function of ABC transporters and autophagy through PTEN/Akt/mTOR signaling pathway." (PMID 36297310, 2022). "Of note, these two pathways can interact since FAK affects the mTOR pathway through PI3K-AKT signaling activation, as demonstrated in a recent study on a breast cancer model, in which FAK inhibition was shown to reduce mTOR activation." (PMID 35875136, 2022). "Prolonged exposure of breast cancer stem cells to rottlerin results in apoptosis, which is correlated with phosphorylated AKT and MTOR suppression, phosphorylated AMPK upregulation and anti-apoptotic BCL2, BCL2L1, XIAP and BIRC2/cIAP1 downregulation." (PMID 36497321, 2022). "Nevertheless, breast cancer with high immune activity not only enriched immune-related gene sets, but also enriched pro-cancer gene sets: KRAS signaling, PI3K/AKT/MTOR signaling, and apical surface gene sets." (PMID 35945417, 2022). "A recent study showed that GRg5 induced breast cancer cell apoptosis and autophagy by inhibiting the PI3K/Akt/mTOR signaling pathway." (PMID 35885925, 2022). "FMD alone would not be sufficient for restoring endocrine sensitivity in all breast cancers, as tumors with constitutive activation of PI3K/Akt/mTOR signaling are likely to be resistant to fasting approaches." (PMID 36046843, 2022). "Everolimus is therefore used for mTOR-positive, hormone receptor-positive, and HER-2-negative advanced breast cancer in clinic to restore hormone sensitivity." (PMID 35402243, 2022). "The goal of the present study was to identify synthetic lethal interactions between proteases and the PI3K/mTOR pathway inhibitors BKM and BEZ in murine breast cancer cells by employing synthetic lethality screens." (PMID 35673573, 2022). "Consistent with this, gene ontology analysis showed that SCA treatment affected autophagy in breast cancer cells, and Kyoto Encyclopedia of Genes and Genomes analysis showed that the PI3K–Akt–mTOR pathway was strongly affected." (PMID 36408240, 2022). "In breast cancer, PI3K/Akt/mTOR pathway is required for the colony‐formation capacity of tumor cells and the maintenance of stem‐like properties." (PMID 36226253, 2022). "It has also been reported that upon adaptation to hormone deprivation, breast cancer cells rely heavily on PI3K signaling and that inhibition of PI3K and mTOR induces apoptosis in these cells." (PMID 35440675, 2022). "Phosphatidylinositol 3-kinase (PI3K), protein kinase B (PKB/AKT) and mechanistic target of rapamycin (mTOR) (PAM) pathways play important roles in breast tumorigenesis and confer worse prognosis in breast cancer patients." (PMID 36010585, 2022).
breast cancer (continued). "Everolimus is an oral inhibitor of the mammalian target of rapamycin (mTOR) with anti-cancer activity in multiple tumor types, including renal cell carcinoma (RCC), mantle cell lymphoma, breast cancer, and well-differentiated NENs." (PMID 35641203, 2022). "MiR-424-5p has been shown to reduce chemoresistance and decrease breast cancer proliferation by inducing apoptosis and targeting the PI3K/Akt/mTOR pathway." (PMID 36555616, 2022). "Two of these agents, the mTOR inhibitor, everolimus, and α-specific PI3K inhibitor, alpelisib, are now established and licensed drugs for the treatment of advanced ER+ breast cancer when used in combination with ET." (PMID 36046843, 2022). "For patients with HER2+ breast cancer, inhibition of PI3K or mTOR can become a new therapeutic regimen after secondary resistance to anti-HER2 therapy." (PMID 36010585, 2022). "In the mouse model of breast cancer, the administration of dapagliflozin decreased tumor growth, and the AMPK/mTOR pathway is considered a potential regulator of this." (PMID 36046822, 2022). "The Phosphatidylinositol-3-kinase/mammalian Target of Rapamycin (PI3K/mTOR) signaling pathway regulates essential physiological processes 6-8 and is activated in 70% of breast cancer cases 9-12." (PMID 35673573, 2022). "In a study on breast cancer cells, treatment with 5 and 10 μM cepharanthine was found to reduce the levels of both phosphorylated AKT and mTOR." (PMID 36558061, 2022). "Because of its effects on the PI3K/AKT/mTOR pathway, overexpression of OGN dramatically reduces cell growth in breast cancer cells, demonstrating that OGN is a tumor suppressor in breast cancer." (PMID 36421687, 2022). "In breast cancer, silibinin was able to induce autophagy in MCF-7 cells by decreasing Akt/mTOR expression, thus enhancing its inhibitory effect on estrogen receptors and finally causing breast cancer cell death." (PMID 35401195, 2022). "In the first place, combination therapy induced 4T1 and MDA-MB-231 breast cancer cell apoptosis via the activation of the JNK signaling pathway, inhibiting the AKT/mTOR signaling pathway and down-regulating the Bcl-2 and IAP family." (PMID 34282830, 2022). "With the approval of the mTOR complex 1 (mTORC1) inhibitors Everolimus and Temsirolimus for breast cancer and renal cell carcinoma, several inhibitors of PI3K/mTOR have been widely developed and clinical trials have been evaluated." (PMID 36114703, 2022). "Activating Akt, the upstream signaling of mTOR was partially ascribed to MPA-induced resistance in EC and breast cancer." (PMID 36293372, 2022). "OGN can inhibit breast cancer cell proliferative and invasive properties via mediating PI3K/Akt/mTOR signaling pathway." (PMID 35837663, 2022). "In a phase II clinical trial, the mTOR inhibitor sirolimus combined with trastuzumab was well tolerated in patients with trastuzumab-resistant, HER2-positive and advanced breast cancer." (PMID 36010585, 2022). "Previous studies showed that activation of CB1 and CB2 in breast cancer suppressed ERK1/2 and AKT/mTOR signaling pathways." (PMID 35513484, 2022). "TBMS I can induce the autophagy of breast cancer MDA-MB-231 cells, and its effect is achieved by regulating the activity of PI3k-Akt-mTOR signaling pathway." (PMID 36160391, 2022). "FKBP4 expression was also found to be upregulated in breast cancer, in NSCLC by activating the Akt-mammalian target of rapamycin (mTOR) signaling pathway, and in colorectal cancer in males." (PMID 36675710, 2022). "PARP1-ACSL1 pair significantly correlated with poor overall survival in breast cancer owing to the suppression of the MAPK, mTOR and NF-kB signaling pathways, which induces apoptosis, autophagy and prevents inflammatory processes." (PMID 35739271, 2022).
breast cancer (continued). "Cav-1 activates PI3K/Akt/mTOR pathway under low shear stress and promotes motility and a metastatic phenotype of MDA-MB-231 breast cancer cells, therefore plays a role in disseminated cells to blood and lymphatic vessels." (PMID 35163745, 2022). "CXCR4 plays a role in the growth and metastasis of breast cancer via its ligand CXCL12/SDF-1, which activates mTOR to promote the epithelial–mesenchymal transition (EMT), and is therefore important in metastasis." (PMID 35754051, 2022). "Jasmonic acid induces biological activity in Arabidopsis and selectively inhibits breast cancer cell growth via CDC6 and mTOR." (PMID 36531013, 2022). "It is known that mTOR and HDAC enzymes play essential roles in the development of breast cancer brain metastasis." (PMID 36267272, 2022). "We found that gAcrp significantly suppressed phosphorylation of mTOR in MCF-7 and MDA-MB-231 breast cancer cells." (PMID 34986886, 2022). "For example, PI3K/AKT/mTOR signal up-regulation stimulates breast cancer progression, and PI3K/AKT/mTOR axis inhibitors have shown positive significance in breast cancer treatment." (PMID 35313850, 2022). "In the context of ER+ breast cancer, the rationale for targeting the PI3K/Akt/mTOR pathway is to overcome resistance to ET by reducing proliferation driven by ligand-dependent activation and inhibiting ligand-independent activation of the ER." (PMID 36046843, 2022). "In breast cancer, in model autoimmune diseases, as in TED, the binding of IGF-1 to IGF-1R triggers the PI3K/AKT/mTOR signaling pathway." (PMID 35784325, 2022). "As a matter of fact, blockade of miR-21 in estrogen receptor-alpha positive (ER+) breast cancer lines with miRNA inhibitors leads to higher therapeutical benefits, as seen by induction of autophagic cell death through inhibition of the PI3K-Akt-mTOR pathway." (PMID 35309939, 2022). "This in vitro study was the first of its kind, proving the potential efficacy of ibrutinib in breast cancer, especially when combined with PI3K/mTOR inhibitors." (PMID 35456016, 2022). "First, the Western blot analysis has shown that mTOR is upregulated in colon cancer (HT-29 and SW620) vs. normal colon (FHC) cells, in breast cancer (MDA MB 231, MCF-7) vs. normal breast (HMEC) cells, in lung cancer (A549 and H1299)." (PMID 36077039, 2022). "In breast cancer, then a downstream molecule of the AKT/mTOR pathway phosphorylates ERα which binds to promoter of target genes, and upregulates IGF-1, IGF-1R." (PMID 35784325, 2022). "In breast cancer cells, HIF-1α proteins decreased due to downregulation of the PI3K/Akt/mTOR pathway." (PMID 35682652, 2022). "For example, Sox2‐overexpressed breast cancer cells exhibit downregulated AMPK signalling and activated mTOR to maintain their cancer stem‐like phenotypes." (PMID 36114703, 2022). "To study a possible connection of Usp7 to PI3K signaling, we examined the activity of the PI3K pathway by phosphorylation status of three players (Akt, mTOR, S6) upon USP7 knockdown in human breast cancer cells." (PMID 35673573, 2022). "Overall, these data suggested that mTOR activation is critical for the effects of ATRAP in increasing metabolism and invasiveness of breast cancer cells." (PMID 35414770, 2022). "Because it inhibited the PI3K/Akt/mTOR signaling pathway and has been proven to reduce breast cancer stem cells (CD44+/CD24), it was identified as a candidate for the treatment of breast cancer." (PMID 36233051, 2022). "PI3K/Akt/mTOR and CDK 4/6/RB pathways have been extensively explored in endocrine resistance in breast cancer." (PMID 36229710, 2022).
breast cancer (continued). "Three patients (2.8%) were converted to mTOR-inhibitor due to HCC recurrence, breast cancer and colon adenocarcinoma at 58, 89 and 112 months, respectively." (PMID 36601628, 2022). "Levobupivacaine inhibited breast cancer cell proliferation and induced apoptosis through inhibition of PI3K/AKT/mTOR signaling pathway." (PMID 35246010, 2022). "Alpelisib (PI3K inhibitor) and everolimus (mTOR inhibitor) have been approved by the U.S. Food and Drug Administration (FDA) for the clinical treatment of breast cancer." (PMID 36010585, 2022). "Among the various mechanisms mediating drug resistance to CDK4/6 inhibitors found in HR‐positive/HER2‐negative breast cancer cells, upregulation of the PI3K/mTOR pathway is a very common one, making it a potential target for reversal of drug resistance." (PMID 38089455, 2022). "In approximately 30–40% of breast cancer cases, especially HR+ subtypes, activation of the PI3K/AKT/mTOR signaling pathways are seen." (PMID 36358806, 2022). "Statistically, the colon and lung cancer specimens expressed comparable mTOR levels when compared to PCa samples in the TMA, while breast cancer specimens expressed lower levels of mTOR protein than the PCa specimens." (PMID 36077039, 2022). "Blocking the PI3K/Akt/mTOR pathway enhances the radiation response of breast cancer models in vitro, and phase II clinical trials have shown that CCI-779, an mTOR inhibitor, is an effective treatment for breast cancer." (PMID 36059650, 2022). "In addition, ACSL4 may be an effective therapeutic target for the regulation of multiple transporters associated with anti-cancer resistance through the mammalian target of rapamycin (mTOR) pathway, thereby restoring drug sensitivity in breast cancer with poor prognosis." (PMID 35910359, 2022). "It has also been shown to modulate a variety of key signaling pathways of JAK/STAT, NF-ĸB, Wnt/β-catenin, PI3K/Akt/mTOR, MAPK, apoptosis, and cell cycle pathways involved in breast cancer progression and development." (PMID 35216255, 2022). "mTOR is a downstream target of the PI3K-protein kinase B (AKT) pathway, which is often reactivated in HR-positive breast cancer cells, resulting in resistance to hormonal therapy." (PMID 35089453, 2022). "In breast cancer, a combination of emodin (10 μM) and berberine (10 and 5 μM) synergistically repealed the SIK3/mTOR pathway." (PMID 36080219, 2022). "PI3K/mTOR signaling inhibition in PIK3CA-mutant and wild-type PIK3CA ER+ breast cancer cells reduced Mcl-1 levels." (PMID 35053443, 2022). "Using the breast cancer cell lines MCF-7 and MDA-MB-231, we observed that masitinib inhibits the activity of mTOR, a downstream effector of EGFR." (PMID 36204232, 2022). "Those that have already been approved, including a PI3K inhibitor (alpelisib) and an mTOR inhibitor (everolimus), provide more options for patients with HR‐positive/HER2‐negative advanced breast cancer after disease progression with endocrine therapy." (PMID 38089455, 2022). "Systemic treatment of hormone receptor-positive (HR+) breast cancer is undergoing a renaissance, with a number of targeted therapies including CDK4/6, mTOR, and PI3K inhibitors now approved for use in combination with endocrine therapies." (PMID 33671468, 2021). "In breast cancer, constitutive expression of MAPK/ERK and PI3K/Akt/mTOR signal pathways are significant events that promote cancer cell growth, survival, and metastasis." (PMID 34603386, 2021). "We also elucidated the mechanism of GABARAP in the inhibition of EMT in breast cancer cells, which is partially dependent on the AKT/mTOR signaling pathway." (PMID 33591943, 2021). "Given that PLD2 is mandatory for mTOR and S6K signaling in MDA-MB-468 breast cancer cells, it can be concluded that this pathway was most likely involved in MDA-NEO and MDA-HER2 cell migration since both cell lines were derived from MDA-MB-468 cells." (PMID 33832505, 2021).
breast cancer (continued). "One of the most commonly altered pathways driving breast cancer cell growth, survival, and motility is the PI3K/AKT/mTOR signaling cascade." (PMID 34298731, 2021). "Another important regulator of the mTOR and ERK-1/2 signaling pathway is AKT, which is commonly altered among the CA cohort of breast cancer patients compared to AA counterparts." (PMID 33996789, 2021). "Here, we review the role of the HER2 receptor, mTOR pathway, and glycolysis in HER2-positive breast cancer, along with signaling mechanisms and the efficacy of treatment strategies of HER2-positive breast cancer." (PMID 34208071, 2021). "Asperolide A, a marine-derived agent, attenuates breast cancer-induced osteolysis through the inhibition of osteoclast differentiation and bone resorption by blocking the PI3K/AKT/mTOR/c-FOS/NFATc1 axis." (PMID 34064589, 2021). "In breast cancer, PCAT6 acts as a sponge for miR-4723-5p to regulate VEGFR2, and also participates in the VEGFR/AKT/mTOR signaling pathway to accelerate angiogenesis." (PMID 34327141, 2021). "This study evaluates the activity of three different PI3K/AKT/mTOR inhibitors, i.e., BEZ235, everolimus and TAK-228 in vitro, in a panel of HER2-positive breast cancer cell lines with primary and acquired resistance to trastuzumab." (PMID 34204960, 2021). "The mammalian target of rapamycin (mTOR) inhibitor—everolimus—and the CDK4/6 inhibitors—palbociclib and ribociclib—have been approved to treat breast cancer patients who are HER2-negative and hormone receptor (HR)-positive." (PMID 35056985, 2021). "In breast cancer cell lines, 4-OXO-DHA induced PPARɣ and 15-hydroxyprostaglandin dehydrogenase (15-PGDH) but inhibited the activity of NF-κB and suppressed PI3K and mTOR signaling." (PMID 33431978, 2021). "Insulin-like growth factor-1 receptor (IGF-1R) is indicated in breast cancer development, progression, and metastasis through its involvement in Ras/Raf/MEK1/2/ERK1/2 and PI3K/AKT/mTOR pathway." (PMID 33841325, 2021). "Oestrogen has previously been implicated in altering pathways related to translation and RNA processing in breast cancer cells, particularly PI3K/AKT/mTOR signalling." (PMID 34576208, 2021). "The inhibition of this pathway by specific PI3K and mTOR inhibitors (LY294002 and rapamycin, respectively) led to a reduction of cell survival and tumorigenicity of the putative breast cancer stem MCF-7 cell population, defined by the side population assay." (PMID 34207464, 2021). "In summary, USP32 knockout sensitized breast cancer cells to YM155-mediated DNA damage and promoted cell apoptosis by inhibiting the PI3K/AKT/mTOR pathway and survivin protein level." (PMID 34815782, 2021). "We verified the effects of ruthenium-fluvastatin complex treatment on various proteins like PI3K, Akt, mTOR, EGFR, VEGF, and cleaved caspase-3 in MCF-7 and MDA-MB-231 human breast cancer cells." (PMID 34221232, 2021). "The knockdown of RPS27L induces autophagy in breast cancer MB231 and SK-BR3 cells by shortening the protein half-life of β-TrCP which is involved in the degradation of DEPTOR, the natural inhibitor of mTOR." (PMID 34873618, 2021). "In breast cancer cells, treatment with Palbociclib, a CDK4/6 inhibitor, upregulates mechanistic target of rapamycin (mTOR) whilst promoting G0/G1 cell cycle arrest." (PMID 33124043, 2021). "In these subtypes of breast cancer, the mechanism of activation of the PI3K/AKT/mTOR pathway is largely determined by genomic changes in these phosphatases." (PMID 34202777, 2021).